U6 (U6 spliceosomal RNA )
Synonyms: LOC124902819
Gene: Small nuclear RNA gene on chromosome 11 (132,525,809 to 132,525,887, forward strand). Ensembl gene ENSG00000283489.
Gene Ontology:
Molecular function: U4 snRNA binding
Biological process: formation of quadruple SL/U4/U5/U6 snRNP; spliceosomal tri-snRNP complex assembly
Cellular component: U4/U6 x U5 tri-snRNP complex; U6 snRNP
Homologues: Orthologues: chimpanzee U6 (99% identical), macaque U6 (80% identical), dog U6 (56% identical), zebrafish U6 (51% identical), mouse Gm55465 (49% identical), guinea pig U6 (47% identical). Paralogues in human: RNU6-1251P (76% identical), RNU6-10P (73% identical), RNU6-1122P (73% identical), RNU6-1152P (73% identical), RNU6-116P (73% identical), RNU6-1201P (73% identical), RNU6-1266P (73% identical), RNU6-15P (73% identical), RNU6-16P (73% identical), RNU6-263P (73% identical), RNU6-33P (73% identical), RNU6-47P (73% identical), and 1284 more.